CDK4 (cyclin dependent kinase 4)
Diseases named in the same sentence as CDK4 in open-access papers (continued):
Sharing a sentence is not in itself a finding about the gene and the disease.
cancer (continued). "Given the critical role of CDK4/6 in cell cycle and the apparent success of CDK4/6 inhibitors against certain cancer, this study attempted to utilize hydrophobic tagging technology to develop a CDK4/6 degrader against TNBC." (PMID 35479314, 2022). "For instance, targeting CDK4 and 6 with inhibitors (such as palbociclib, ribociclib and abemaciclib) induced senescence in various cancer models." (PMID 36067171, 2022). "It is well documented that the exposure to CDK4/6 inhibitors induces cellular senescence in a variety of cancer cell models and the acquisition of a senescent phenotype has been described also in MPM cell lines." (PMID 36497412, 2022). "The inhibition of CDK4/6 with palbociclib has been reported to stimulate PD-L1 expression in cancer cells by inhibiting ubiquitination-mediated PD-L1 degradation." (PMID 35884422, 2022). "Numerous clinical trials are ongoing to assess CDK4/6i in combination therapy to treat breast and additional cancer types." (PMID 36185294, 2022). "The potent immunomodulatory effects of CDK4/6i have prompted clinical trials evaluating CDK4/6i in combination with ICI for the treatment of various cancer types (NCT02791334, NCT04118036, NCT02778685, NCT04075604, NCT02779751)." (PMID 35444175, 2022). "Meanwhile, depletion of HMGB1 and ly294002 promoted apoptosis and arrested the cancer cells in G0/G1 cell cycle with the decreased expression of Cyclin D1 and CDK4 and improved P16." (PMID 36260180, 2022). "It is established that cancer cells with malfunctioning RB pathways are mostly resistant to the treatment with CDK4/6i17." (PMID 35948546, 2022). "Recent studies demonstrated that the CDK4/6 inhibitors exhibit potent growth-inhibitory activity in various cancers in vitro and in animal studies." (PMID 35269749, 2022). "Small molecule compounds specifically targeting cell cycle kinases, including the CDK4/6 inhibitors, are new agents found to have activity in cancer treatment, and are commonly used in metastatic breast cancer." (PMID 36185294, 2022). "Dysregulation of the cyclin D–CDK4/6–INK4–Rb pathway results in increased proliferation and due to the importance of CDK4/6 activity in cancer cells, CDK4/6 inhibitors seem as promising treatment." (PMID 36531058, 2022). "A major finding of this study is that CDK4/6 inhibitors, like many other broad‐spectrum anti‐cancer drugs, induce genotoxic stress during S‐phase." (PMID 35037284, 2022). "In cancer cells, CDK4/6 are usually overactivated by their upstream oncogenes (e.g. c-myc) and serve as potential targets for cancer therapies." (PMID 35410300, 2022). "This dependence on MAPK activation suggests that combinatorial treatment with MAPK and CDK4/6 inhibitors is a potentially effective cancer treatment strategy." (PMID 35938171, 2022). "The expression of CCND1 and CDK4/6, which are well-acknowledged regulator not only in cell cycle but also in cancer progression, was also found to be downregulated upon CDCA8 knockdown 37-39." (PMID 35517403, 2022). "We set forth to evaluate the efficacy of CDK4/6 inhibitor and oxaliplatin combination therapy for preventing cancer drug resistance." (PMID 35664774, 2022). "Data has shown that RB1 exists in S249/T252 in the form of CDK4/6 phosphorylation, which can counteract cancer immune evasion." (PMID 35299734, 2022). "Recent studies have demonstrated the high potency of Erk1/2 and CDK4/6 inhibitors in metastatic relapsed cancers, and here we tested anti-MM effects of the Erk1/2 + CDK4/6 inhibitor combination." (PMID 35082402, 2022). "This review discusses the role that CDK4 plays in cell cycle control, normal development and tumorigenesis as well as the current status and utility of approved small molecule CDK4/6 inhibitors that are currently being used as cancer therapeutics." (PMID 36051751, 2022). "In several cancers, including GBM, the CDK4/6-cyclin D-Rb-E2F pathway is excessively activated to promote cancer cell proliferation." (PMID 36432068, 2022).
cancer (continued). "A previous study indicated that RB is a direct downstream protein of CDK4/6 complex and its action determined anti-cancer activity of palbociclib." (PMID 36005200, 2022). "As a result, there are now more than 100 clinical trials that attempt to combine CDK4/6 inhibitors with targeted therapies, chemotherapies or immunotherapy for development of more superior anti-cancer treatment options." (PMID 35058574, 2022). "The significance of the CyclinD-CDK4/6-Rb-E2F pathway in controlling G1/S transition during cell cycle progression has led to the development of CDK4/6 inhibitors for clinical cancer therapy." (PMID 35449080, 2022). "The qRT-PCR-based evidence showed that Far-C mediated the reduced mRNA expression of both cyclinD1 and CDK4 in HepG2 cells, which has previously been reported to be responsible for arresting the progression of cancer cells to the G0/G1 phase of cell cycle." (PMID 36145291, 2022). "Cyclin-dependent kinase 4/6 (CDK4/6) are key regulators of the cell cycle and are deemed as critical therapeutic targets of multiple cancers." (PMID 35327487, 2022). "Anti‐Chi3L1 antibody significantly decreased the expression of cancer growth and migration‐associated proteins, such as PCNA, cyclin D1, cyclin E, Cdk2, Cdk4, Cdk5, MMP2 and MMP9 in A549 lung metastasis model tissues." (PMID 34861103, 2022). "Aberrant activation of CDK4, one of the eight positive regulators of the G1/S transition, is frequently seen in various cancers, including HCC." (PMID 33686022, 2021). "Here, we have described the refinement of the PDS model to suit anti-cancer drug validations and further analyzed the effect of endocrine therapies and the CDK4/6-inhibitor palbociclib in PDS cultures using ERα-positive cancer cell lines." (PMID 34172801, 2021). "In summary, in cell-cycle–altered cancers, matched CDK4/6 inhibitors, as part of an individualized regimen targeting a majority of genomic alterations, was independently associated with longer PFS." (PMID 33427211, 2021). "CDK4/6 inhibitors (CDK4/6i) have been evaluated in clinical trials in many cancer types with promising results." (PMID 33122824, 2021). "In vitro and in vivo investigations revealed that CDK4/6 inhibitors suppress the proliferation of many different malignant tumor cells." (PMID 34395284, 2021). "Cyclin D/cyclin G2 and CDK4/6 have been shown to be upregulated in a variety of human cancer cells 40-42." (PMID 33390846, 2021). "As senescence has been previously shown to alter cancer progression as well as therapy response, we sought to identify vulnerabilities of CDK4/6 inhibitor-induced senescent cells." (PMID 34944934, 2021). "Owing to the significance of CDK4/6 kinases in the regulation of cell proliferation, CDK4/6 inhibitors have undergone clinical trials for several malignant tumors." (PMID 34395284, 2021). "This suggests the potential of NSC765600 and NSC765691 to inhibit CCND1/CDK4/PLK1/CD44 expressions in cancer." (PMID 34063946, 2021). "More relevant to our model, proliferation can also be evoked by the presence of low concentrations of p21 protein (not a complete knock-out), through the assembly and activation of cyclin D/Cdk4 or Cdk6 complexes, as shown in cancer cell lines." (PMID 33925586, 2021). "The complex interactions among oncogenic signaling, epigenetics and viral mimicry can be further demonstrated by the effects of the cyclin-dependent kinases 4 and 6 (CDK4/6) on cancer immunity." (PMID 33668131, 2021). "Unfortunately, faced with clinical data, either CDK4/6 or mTOR inhibitors are found to have clinical limitations as single agents in cancer therapy, as some patients develop clinical resistance." (PMID 35008317, 2021).
cancer (continued). "Cyclin D1 is amplified and overexpressed in multiple cancers and the cyclin D1/CDK4/6 holoenzyme complex is stimulated by mitogenic signaling cascades to accelerate cancer cell proliferation." (PMID 34831218, 2021). "We further extended our analysis on other members of RB1 pathway, including CDKN2A (p16Ink4a), CCND1, CDK4, and CDK6, which are often mutated in different cancers." (PMID 33591981, 2021). "The in vivo results suggest a therapeutic potential of the CDK4/6/HSP90 dual inhibition strategy in cancer treatment." (PMID 34686682, 2021). "Specifically, CDK4, as a cell cycle regulatory protein, can play an essential regulatory role in the G1-S phase of cancer cells, thereby affecting the proliferation of cancer cells and promoting cancer progression." (PMID 34784846, 2021). "Clinical trials or preclinical studies on CDK4/6 inhibitors have been implemented for some malignant tumors." (PMID 34395284, 2021). "Increasing evidence has suggested that CDK4/6 play important roles in the progression and prognosis of multiple cancers, including OC." (PMID 35095879, 2021). "At the same time, we found that the expression level of CDK4 also changes during the period of cancer." (PMID 34784846, 2021). "The CDK4 axis is altered in many cancers, with clinically approved pharmacological inhibitors showing promising antitumor activity." (PMID 34309585, 2021). "With the success of CDK4/6 inhibitors in treating breast cancers, and likely other cancers in the near future, understanding their mechanism of action and interaction with other therapies is vital in their clinical development." (PMID 33572972, 2021). "Overall, our study highlights a wide-spread reduction in sensitivity to anti-cancer drugs accompanied with an acquired vulnerability to EGFR inhibitors following CDK4/6 inhibitor treatment." (PMID 34944934, 2021). "Currently, CDK inhibitors such as CDK4/6 inhibitors are used in pre-clinical studies for cancer treatment." (PMID 35002699, 2021). "These high binding affinities resulted in promising anti-tumor activity across a variety of cancer cell lines through the degradation of cancer-related Hsp90 client proteins such as Akt and CDK4." (PMID 34831072, 2021). "Augmented CDK4/6 activity is observed in many cancers in addition to melanoma, making it an attractive therapeutic target for the treatment of a variety of malignancies." (PMID 34025662, 2021). "It was also observed that ribociclib, a cyclin-dependent kinase inhibitor that slows cancer cell growth by inhibiting CDK4/6 proteins, significantly decreased viability in the healthy cell line in addition to its effect in the carcinoma cell line." (PMID 36303724, 2021). "In the presence of increased cellular glucose, PRMT5 has been shown to stimulate the release of cyclin dependent kinase 4 (CDK4) from its inhibitor, promoting G1-S transition in cancer cells." (PMID 33440687, 2021). "For instance, HPV- cancers often have gene copy gains in CCND1 (which encodes for cyclin D1) and amplifications and activating mutations of CDK4." (PMID 34490123, 2021). "First, proteins related to the cell cycle, such as cyclin D1, cyclin E, and CDK4, can promote cell proliferation in normal and cancer cells." (PMID 33722298, 2021). "Based on these results, research efforts are currently being directed toward the development of anti-cancer treatment strategies based on utilisation of CDK4 as a target." (PMID 34930213, 2021). "The inhibitor of CDK4/6 has been clinically used for treating certain types of cancer which are characterized by G0/G1 acceleration induced by the CDK4/6-RB1 pathway." (PMID 34513922, 2021). "CDK4, a serine/threonine kinase that modulates cell cycle entry through the phosphorylation of RB, is frequently activated in human cancers and has become a common target of interest for new therapeutics." (PMID 34828525, 2021).
cancer (continued). "With p21 overexpression in mesenchymal cancer cells, we detected increased CDK4-p21 complex and reduced in vitro and in vivo growth of tumors." (PMID 34309585, 2021). "Recently, CDK4-targeted therapy has attracted attention as a potential therapeutic target for some cancers." (PMID 34395284, 2021). "Scientists designed the CDK4/6 inhibitors to treat cancer based on this target 11-14, but it doesn't work in some tumor patients or cancer cells unexpectedly 15-18." (PMID 34335935, 2021). "Several preclinical studies have consistently shown that CDK4/6 inhibitors lead to autophagy activation in different cancer cells." (PMID 35008317, 2021). "In summary, we found that CDK4/6 were highly expressed in multiple types of human cancers (including OC) and negatively correlated with a good prognosis in OC patients." (PMID 35095879, 2021). "Despite the efficacy of CDK4/6 inhibition, a subset of cancers (10–20%) remain insensitive and a large percentage (70–80%) becomes resistant after 12–36 months of therapy." (PMID 33741974, 2021). "CDK4 is frequently dysregulated in cancer, and the development of CDK4-targeted therapies is important." (PMID 34094975, 2021). "The vast alteration in the “miRNome” of cancer cells compared with their normal counterparts provides a rationale of increased or decreased response to CDK4/6 inhibitors." (PMID 34439268, 2021). "Anti-cancer effects of the CDK4/6 inhibitors such as palbociclib, ribociclib, and abemaciclib in various types of cancers have been documented and these have all underwent phase III clinical trials 27-30." (PMID 34335925, 2021). "Glutamine feeds into the tricarboxylic acid (TCA) cycle within the mitochondria to fuel oxidative metabolism and has been shown to drive CDK4-dependent metabolic reprogramming within other cancer types." (PMID 33572972, 2021). "The use of cyclin-dependent kinase 4/6 (CDK4/6) inhibitors represents a potent strategy for cancer therapy." (PMID 33923231, 2021). "Several previous studies have proposed the CDK4/6 axis as a rational therapeutic target for cancer treatment." (PMID 34099764, 2021). "Increased dependence on CDK4 rendered mesenchymal cancer cells particularly vulnerable to selective CDK4 inhibitors." (PMID 34309585, 2021). "Relative to normal colorectum tissue, gene expression of CDK-1 and CDK-4 were up-regulated in all major forms of cancer with high mRNA expressions observed in CRC." (PMID 33732631, 2021). "ILD is a well-recognized, potentially serious complication of many different cancer agents and a class side effect of CDK4 and CDK 6 inhibitors." (PMID 33797023, 2021). "The cyclin D (CCND)–cyclin-dependent kinase 4/6 axis (CDK4/6), which modulates the transition through the G1 phase to S phase of the cell cycle, plays a key role in the pathological process of many cancer types." (PMID 33845905, 2021). "In this study, we used public data to analyze the expression and prognostic impact of CDK4/6 in many human cancers, including OC." (PMID 35095879, 2021). "Out of these proteins, the CDK4 is a regulatory component of the DC complex which is a major integrator of various mitogenic and antimitogenic signals, and plays a vital role in cancer." (PMID 33438725, 2021). "Small-molecule inhibitors against cyclin-dependent kinase 4/6 (CDK4/6) are potent compounds for cancer treatment." (PMID 33923231, 2021). "Previous studies investigating the mechanism of action of CDK4/6 inhibitors have used cancer cells, where the extent to which cell cycle control networks are perturbed is poorly understood." (PMID 34784791, 2021). "Most of the journals that published data on CDK4/6 inhibitors are in the field of cancer research, especially basic research." (PMID 33995631, 2021). "Conversely, CDK4/6i-resistant cells were sensitive to MEKi, indicating cancer cell dependence on the MAPK signaling in growth and invasion." (PMID 33807122, 2021).
cancer (continued). "Recent successes with CDK inhibitors, such as those that target CDK4, are encouraging, since these inhibitors block the proliferation of cancer cells." (PMID 33996588, 2021). "In vitro analyses were done to determine efficacy of the selective CDK4/6 inhibitor palbociclib on HPVU cancer cell lines." (PMID 34572780, 2021). "After palbociclib, two CDK4/6 inhibitors, ribociclib and abemaciclib, were approved as anti-cancer drugs." (PMID 34686682, 2021). "↓ mTOR and STAT3 pathway signalling in response to a CDK4/6 inhibitor repressing the stemness of HNSCC cancer cells." (PMID 34137158, 2021). "This work clarifies our current understanding of the mechanism of action of CDK4/6 inhibitors and has implications for cancer treatment and patient stratification." (PMID 34784791, 2021). "Nonetheless, relatively little is known regarding how cancer cells adapt to drug presence upon prolonged CDK4/6i treatment." (PMID 34508104, 2021). "CDK4/6 is required for cell cycle entry, and is also attractive target for new developments in cancer therapeutics." (PMID 33767584, 2021). "The differentiation ability of the human cancer cells A549 is decreased by β-sitosterol, which also induces G0/G1 cell cycle arrest, decreased CDK4 and cyclin D1 levels, and increased expression of p21/Cip1 and p27/Kip1." (PMID 34679718, 2021). "Based on these promising results, great hopes are now pinned on the use of CDK4/6i in different cancers types, especially when used in combination with other targeted therapies or chemotherapy." (PMID 34654798, 2021). "When analyzing correlates of response at the gene level, CDKN2A, a tumor suppressor gene that inhibits CDK4/6 activity and is frequently deleted across cancers, was the strongest correlate of response to atezolizumab." (PMID 34172722, 2021). "Cyclin-dependent kinase 4 (CDK4) is a downstream effector of growth factor activation, involved in the p16INK4a-CDK4-Rb axis in cancer development, which has a significant role in AML." (PMID 33401428, 2021). "The genes involving cell cycle control, DNA replication, apoptosis, senescence and autophagy in cancer pathways including CDK4, E2F1, Bax, CDKN1A, GADD45A, FAS, GABARAPL2, and SQSTM were significantly upregulated." (PMID 34305605, 2021). "The use of CDK4/6 inhibitors in the treatment of a wide range of cancers is an area of ongoing investigation." (PMID 34784791, 2021). "This suggests the potential of NSC765600 and NSC765691 compounds to inhibit CCND1/CDK4/PLK1/CD44 expressions in cancer." (PMID 34063946, 2021). "This apparent contradiction to previous studies 37 is likely explained by the fact that the effectiveness of FOXM1 or CDK4/6 targeting is conditioned by the set of molecular alterations present in cancer cells." (PMID 34646365, 2021). "To further demonstrate this point, we coimmunoprecipitated CDK4 and p21 from mesenchymal-like and epithelial-like cancer cells." (PMID 34309585, 2021). "Numerous studies have demonstrated that abnormal CDK4 levels or activation states are closely related to tumourigenesis and progression of various cancers." (PMID 34930213, 2021). "As in these malignant tumors, CDK4/6 inhibitors are also anticipated to be valuable for unresectable EMPD." (PMID 34395284, 2021). "There are >100 active clinical trials testing efficacy of CDK4/6 inhibitors across many cancer types and treatment strategies, exemplifying its value as a candidate for future cancer therapy." (PMID 33741974, 2021). "CDK4/6 inhibitors (CDK4/6i) also induce cellular senescence in cancer cells promoting in parallel autophagy." (PMID 35008317, 2021). "The inhibition of CDK4/6 has therefore gained substantial interest in the hope of new and effective therapeutics in multiple cancers, such as advanced metastatic breast cancer." (PMID 34828525, 2021).